SARNP (SAP domain containing ribonucleoprotein)
Description:
Binds both single-stranded and double-stranded DNA with higher affinity for the single-stranded form. Specifically binds to scaffold/matrix attachment region DNA. Also binds single-stranded RNA. Enhances RNA unwinding activity of DDX39A. May participate in important transcriptional or translational control of cell growth, metabolism and carcinogenesis. Component of the TREX complex which is thought to couple mRNA transcription, processing and nuclear export, and specifically associates with spliced mRNA and not with unspliced pre-mRNA. The TREX complex is recruited to spliced mRNAs by a transcription-independent mechanism, binds to mRNA upstream of the exon-junction complex (EJC) and is recruited in a splicing- and cap-dependent manner to a region near the 5' end of the mRNA where it functions in mRNA export to the cytoplasm via the TAP/NXF1 pathway. Associates with DDX39B, which facilitates RNA binding of DDX39B and likely plays a role in mRNA export.
Synonyms: HCC1; HSPC316; THO1; Hcc-1; CIP29
Tractability: PROTAC: ubiquitination databases record sites on it; its protein half-life has been measured.
Gene: Protein-coding gene on chromosome 12 (55,752,463 to 55,817,748, reverse strand). Ensembl gene ENSG00000205323.
Subcellular location: Nucleus; Nucleus speckle
Subcellular location (Human Protein Atlas): Nuclear speckles
Pathways (Reactome):
Metabolism of RNA: Transport of Mature mRNA derived from an Intron-Containing Transcript; mRNA 3'-end processing
Gene Ontology:
Molecular function: protein binding; RNA binding; chromatin binding
Biological process: mRNA export from nucleus; poly(A)+ mRNA export from nucleus
Cellular component: nuclear speck; transcription export complex; nucleoplasm; nucleus
Genetic constraint (gnomAD): Loss-of-function variants: 0 observed, 6.3 expected, observed/expected ratio (o/e) 0, 90% interval 0 to 0.47. That is too few expected variants to judge how well the gene tolerates losing a copy. Missense variants: 54 observed, 69.76 expected, observed/expected ratio (o/e) 0.77, 90% interval 0.62 to 0.97. Synonymous variants: 32 observed, 25.82 expected, observed/expected ratio (o/e) 1.24, 90% interval 0.93 to 1.66.
Homologues: Orthologues: guinea pig Sarnp (98% identical), rabbit SARNP (97% identical), mouse Sarnp (96% identical), pig SARNP (93% identical), rat Sarnp (93% identical), dog SARNP (92% identical), tropical clawed frog sarnp (64% identical), zebrafish sarnp (60% identical), Caenorhabditis elegans Y53G8AR.6 (37% identical).
Diseases named in the same sentence as SARNP in open-access papers:
SARNP is named in the same sentence as 4 diseases in open-access papers, as found by Europe PMC text mining. Sharing a sentence is not in itself a finding about the gene and the disease. The quoted sentences say what the papers report.
glioma (1 paper, 2021). A benign or malignant brain and spinal cord tumor that arises from glial cells (astrocytes, oligodendrocytes, ependymal cells). "Both LSM11 and SARNP played roles in preventing disorders of cell protein synthesis or cell division, and their decreased expression in gliomas may be associated with glioma development." (PMID 34482648, 2021). "LSM11 participated in histone RNA 3’ processing and SARNP, playing a role in mRNA splicing and export, was not only significant in glioma but also acted as an important molecule in triple‐negative breast cancer." (PMID 34482648, 2021).
viral infection (1 paper, 2024). "We found that c-Fos expression was decreased in the PFC of Ube3a 2xTg brains, and this reduction was partially rescued by SARNP viral infection." (PMID 38316900, 2024).
cancer (2 papers, 2016 to 2024). A tumor composed of atypical neoplastic, often pleomorphic cells that invade other tissues. "SARNP is up-regulated in cancer tissues, but a further link to AML has been made attributable to a translocation event creating an SARNP–mixed lineage leukemia (MLL) fusion protein." (PMID 27679854, 2016). "As MLL does not have any intrinsic DNA-binding capability, the SARNP–MLL fusion may confer this action through SARNP's SAP DNA-binding motif, potentially resulting in altered gene expression, a hallmark of cancer development." (PMID 27679854, 2016).
SARNP also shares sentences with these, for which no sentence is quoted: infection (1 paper).